SIRT3 (sirtuin 3)
Diseases named in the same sentence as SIRT3 in open-access papers (continued):
Sharing a sentence is not in itself a finding about the gene and the disease.
alopecia (1 paper, 2024). Hair loss usually from the scalp. "Sirt3 has been shown to be protective of cochlear hair cells, and Sirt3 activators like honokiol and methyl-honokiol have been shown to be beneficial in murine models of alopecia." (PMID 39596133, 2024).
aneurysm (1 paper, 2024). Bulging or ballooning in an area of an artery secondary to arterial wall weakening. "Previous reports have shown that SIRT3 overexpression attenuated aneurysm formation and decreased aortic expansion induced by Ang II." (PMID 39300372, 2024).
anxiety disorder (1 paper, 2022). A category of psychiatric disorders which are characterized by anxious feelings or fear often accompanied by physical symptoms associated with anxiety. "SIRT3 may be an expected target for the treatment and diagnosis of postoperative anxiety disorders." (PMID 35372451, 2022).
Aortic dissection (1 paper, 2025). Aortic dissection refers to a tear in the intimal layer of the aorta causing a separation between the intima and the medial layers of the aorta. "This suggests that Sirt3 may be involved in aortic dissection (AD), warranting further investigation." (PMID 40800583, 2025).
Arrhythmia (1 paper, 2020). Any cardiac rhythm other than the normal sinus rhythm. "With respect to arrhythmia, SirT3 upregulation stimulates Na+/K+-ATPase and thus moderately increases intracellular K+, augmenting the stability of cardiomyocyte membrane potential." (PMID 32721927, 2020).
artery occlusion (1 paper, 2020). "From the perspective of the disease model, scholars have confirmed that SIRT3 is significantly reduced in the ischemic tissue of the rat model of coronary artery occlusion." (PMID 32575874, 2020).
Arthritis (1 paper, 2024). Inflammation of a joint. "IL-1β induces inflammation, mitochondrial dysfunction and chondrocyte degeneration, while Sirt3 in arthritis treatment can ameliorate arthritis severity and joint damage through inhibition of the PI3K/Akt/mTOR pathway." (PMID 38913046, 2024).
B-cell lymphoma (1 paper, 2020). "In particular, compounds 55 (IC50 SIRT2 0.25 μM and <25% inhibition at 50 μM against SIRT1 and SIRT3) and 56 (IC50 SIRT2 0.78 μM and <25% inhibition at 50 μM against SIRT1 and SIRT3) showed apoptotic as well as strong anti-proliferative properties against B-cell lymphoma cells." (PMID 31973227, 2020).
bladder tumor (1 paper, 2021).
calcification (1 paper, 2025). Process by which organic tissue becomes hardened by the physiologic deposit of calcium salts. "Notably, SIRT1, SIRT2, SIRT3, SIRT6, and SIRT7 have demonstrated therapeutic potential in the treatment of vascular calcification." (PMID 41480421, 2025).
carotid artery thrombosis (1 paper, 2021). Blood clot formation in any part of the carotid arteries. "In the LPS-excited laser-induced carotid artery thrombosis model, compared with the Sirt3+/+ wild-type control group, the thrombotic occlusion time in Sirt3−/− mice was reduced by half." (PMID 33680285, 2021).
cerebrovascular diseases (1 paper, 2024). "Our findings open new avenues for exploring SIRT3 as a potential therapeutic target in vascular pathologies and associated end organ damages, particularly in cardiovascular and cerebrovascular diseases." (PMID 39425510, 2024).
cervical squamous cell carcinoma (1 paper, 2023). A squamous cell carcinoma arising from the cervical epithelium. "In cervical squamous cell carcinoma (CESC), ALKBH5 and IGF2BP1 target silent mating type information regulation 2 homolog 3 (SIRT3), reducing its stability, subsequently inhibiting ACC1 deacetylation and lipid metabolism and ultimately repressing CESC." (PMID 37055798, 2023).
cholestasis (1 paper, 2020). Impairment of the bile flow caused by obstruction within the liver, or outside the liver in the bile duct system. "Double-blind scoring showed a significant reduction of number of bile ducts per portal area in the Sirt3−/− irradiated mice, which could contribute to the development of cholestasis and eventually chronic fibrosis." (PMID 32403251, 2020).
chondrosarcoma (1 paper, 2017). A malignant cartilaginous matrix-producing mesenchymal neoplasm arising from the bone and soft tissue. "However, the role of SIRT3 in chondrosarcoma prevention or therapy still remains to be clarified in the future." (PMID 28600541, 2017).
chronic hepatitis (1 paper, 2025). An active inflammatory process affecting the liver for more than six months. "The findings suggest that these agents, as SIRT3 modulators, can be used in preventing or treating oxidative injury to hepatocytes caused by major pathogenesis of various chronic liver diseases, ethanol cellular injury, and chronic hepatitis." (PMID 39859490, 2025).
clear cell adenocarcinoma (1 paper, 2019). A malignant neoplasm composed of glandular epithelial clear cells. "In Hendrix’s dataset, SIRT1, SIRT3, and SIRT4 expression levels were significantly lower in serous, endometrioid, mucinous, and clear cell adenocarcinoma than they were in normal ovarian tissues." (PMID 31572453, 2019).
Co-infection (1 paper, 2014). "Co-infection of lenti-MnSOD122K-R also prevented immortalization of Sirt3-/- MEFs by a single oncogene." (PMID 25332769, 2014). "Furthermore, in several tissue culture experiments, co-infection of lenti-MnSOD not only decreased mitochondrial superoxide levels but also prevented immortalization of Sirt3-/- MEFs by a single oncogene." (PMID 25332769, 2014).
cognitive (1 paper, 2024). "TLB:Improves cognitive deficits in both animal models.Ameliorates neuroinflammation and oxidative stress by inhibiting the HMGB1/TLR4/NF-κB signaling pathway and activating the SIRT3/SOD2 pathway, which helps to restore redox homeostasis and suppress neuroinflammation." (PMID 39459209, 2024).
complication (1 paper, 2020). Any disease or disorder that occurs during the course of, or because of, another disease, treatment, or procedure. "Besides, except for SIRT1, there are still other members of the sirtuin family (e.g., SIRT3, SIRT6, and SIRT7) that are active in modulating vascular function, which inspires further works to investigate their associations with oxidative stress and diabetic vascular complications." (PMID 33304318, 2020).
congestive heart failure (1 paper, 2025). Failure of the heart to pump a sufficient amount of blood to meet the needs of the body tissues, resulting in tissue congestion and edema. "The congestive heart failure-associated targets were Dnmt1, Hdac1, Hdac4, Ezh2, Sirt3, Kdm2a, Prkca and Prkcb (9.8% of total targets)." (PMID 40076868, 2025).
deafness (1 paper, 2025). An inherited or acquired condition characterized by the complete loss of the ability to hear from one or both ears. "Thus, our study explores the role of the deafness gene PRPS1 in HL, particularly through the NAD+/SIRT3/SOD2 pathway." (PMID 40677922, 2025).
diabetic neuropathy (1 paper, 2024). A chronic, pathological complication associated with diabetes mellitus, where nerve damages are incurred due to diabetic microvascular injury involving small blood vessels that supply these nerves, resulting in peripheral and/or autonomic nerve dysfunction. "Painful diabetic neuropathy in the dorsal root ganglion (DRG) induces mitochondrial impairment and sirtuin 3 deficiency, leading to inhibited mitophagy through the FoxO3a‐PINK1‐Parkin pathway, exacerbating allodynia." (PMID 38572816, 2024).
dominant optic atrophy (1 paper, 2021). "Among these were SIRT3 associations with proteins involved in mitochondrial organization, including OPA1, a dynamin-related guanosine triphosphatase mutated in dominant optic atrophy." (PMID 33857259, 2021).
emphysema (1 paper, 2017). "This is corroborated by our findings that mitochondrial antioxidant SOD2 and histone deacetylase SIRT3 were reduced in mouse lungs with emphysema." (PMID 28186975, 2017). "Therefore, the alterations of p66shc, SOD2 and SIRT3 may link mitochondrial ROS, biogenesis and dynamics to cellular senescence during the development of COPD/emphysema." (PMID 28186975, 2017).
Erythema (1 paper, 2023). Redness of the skin, caused by hyperemia of the capillaries in the lower layers of the skin. "The psoriasiform symptoms (scaling, erythema, and skin thickening) in Sirt3-/- mice were similar to those in WT mice but more severe, consistent with our hypothesis." (PMID 37275851, 2023).
erythroleukemia (1 paper, 2020). Acute erythroid leukemia characterised by the presence of at least 50% erythroid precursors and at least 20% myeloblasts in the bone marrow. "The SAP18 agonist compound, A671, with potent inhibitory effect against T-cell lymphoma and erythroleukemia through SIRT3 downregulation needs further investigation for the treatment of these, and other malignancies in which the SAP18/SIRT3 regulatory axis is intact." (PMID 33273692, 2020).
esophageal squamous cell carcinoma (1 paper, 2017). Esophageal squamous cell carcinoma (ESCC) is a type of esophageal carcinoma (EC) that can affect any part of the esophagus, but is usually located in the upper or middle third. "A number of studies have analyzed the clinical significance of SIRT3 expression in esophageal squamous cell carcinoma (ESCC)." (PMID 27686535, 2017).
fatty acid metabolic disorder (1 paper, 2023). "In the present study, we found that age‐related SIRT3 deficiency is critical to fatty acid metabolic disorder during acute ischemia and I/R stress in the heart." (PMID 37537789, 2023).
Fulminant hepatitis (1 paper, 2016). Acute hepatitis complicated by acute liver failure with hepatic encephalopathy occurring less than 8 weeks after the onset of jaundice. "The feature of SIRT3 in oxidative stress regulation may also strongly benefit in the management of fulminant hepatitis caused by viruses, drugs, or toxic agents." (PMID 27483432, 2016).
fungal infections (1 paper, 2017). "We report that SIRT3 deficiency has no major impact on immune cell development and host defenses against bacterial and fungal infections." (PMID 28634345, 2017). "Overall, our data support the assumption that SIRT3 has no major impact on innate immune functions and host defenses against bacterial and fungal infections, at least in healthy immunocompetent hosts." (PMID 28634345, 2017).
glomerulonephritis (1 paper, 2024). A renal disorder characterized by damage in the glomeruli. "DEX administration alleviated glomerulonephritis in the animal model and upregulated SIRT3 expression in the renal tissue." (PMID 38270316, 2024).
glucose metabolism disorders (1 paper, 2023). "SIRT1 and SIRT3 are key melatonin targets; in rats, melatonin efficiently alleviates glucose metabolism disorders by decreasing mitochondrial dysfunction through activating SIRT1 and SIRT3." (PMID 36815979, 2023).
gout (1 paper, 2023). A condition characterized by painful swelling of the joints, which is caused by deposition of urate crystals. "RNA sequencing, bio-informatics analysis, RT-PCR, and Western blot demonstrated that Sirt3 could suppress the expression of Acod1 (Irg1), which plays an important role in gout." (PMID 37468929, 2023).
HCMV infection (1 paper, 2021). "Relative quantification of interactions demonstrated that HCMV infection induces a range of alterations in SIRT3 associations with substrates that function in regulating mitochondrial structure and cellular metabolism." (PMID 33857259, 2021). "Altogether, we highlight SIRT3 activity as a regulatory hub for mitochondrial acetylation and morphology during HCMV infection and point to global acetylation as a reflection of mitochondrial health." (PMID 33857259, 2021). "To investigate SIRT3 function during HCMV infection, we generated fibroblasts stably expressing SIRT3 fused to green fluorescent protein (GFP) (top)." (PMID 33857259, 2021). "Using immunoaffinity purification and mass spectrometry (IP-MS), we characterize the temporal dynamics of SIRT3-substrate interactions during the progression of HCMV infection." (PMID 33857259, 2021). "Given our finding of altered OPA1 acetylation status and interaction with SIRT3 during HCMV infection, we examined its function by performing siRNA-mediated knockdown (siOPA1-KD) and over-expression (OE) studies." (PMID 33857259, 2021). "As mitochondrial structure is altered during HCMV infection, it is possible that one facet of SIRT3 antiviral function is its ability to maintain mitochondrial integrity." (PMID 33857259, 2021). "Altogether, our study highlights the deacetylase activity of SIRT3 as a regulatory hub that can be used to broadly control mitochondrial acetylation, integrity, and metabolism during HCMV infection." (PMID 33857259, 2021). "Here, we investigate the link between SIRT3 function, protein acetylation, and mitochondrial integrity during HCMV infection." (PMID 33857259, 2021). "Considering the global disruption of mitochondria during HCMV infection and the breadth of SIRT3 substrates, it is tempting to propose that SIRT3 executes its antiviral functions via its deacetylation activity and its regulation of both mitochondrial integrity and metabolism." (PMID 33857259, 2021). "In this study, we aimed to decode the dynamics of SIRT3-substrate interactions and the role of the resulting temporal acetylation events on mitochondrial structure, metabolism, and production of virus progeny upon HCMV infection." (PMID 33857259, 2021). "Here, we link the activity of the mitochondrial deacetylase SIRT3 and global mitochondrial acetylation status to host antiviral responses via regulation of both mitochondrial structural integrity and metabolism during HCMV infection." (PMID 33857259, 2021). "Given the knowledge that, in uninfected cells, SIRT3 has the ability to remove the OPA1 inhibitory acetylation at K931, we first investigated this residue in the context of HCMV infection." (PMID 33857259, 2021).
hepatitis B (1 paper, 2024). "SIRT3 also has a rolein infectious diseases such as hepatitis B. SIRT3 is involved in covalentlyclosed circular DNA (cccDNA) transcription and particularly has anantiviral activity through epigenetic regulation." (PMID 38261767, 2024).
Hyperammonemia (1 paper, 2023). An increased concentration of ammonia in the blood. "We overexpressed Sirt3 in differentiated murine myotubes and showed that this results in maintained Sirt3 activity during hyperammonemia." (PMID 37101412, 2023). "Hyperacetylation of mitochondrial proteins during hyperammonemia are consistent with decreased expression and activity of Sirt3, the primary mitochondrial deacetylase." (PMID 37101412, 2023). "Compared to genetic approaches to oxidize NADH, Sirt3 overexpression restored only some of the hyperammonemia‐induced perturbations and may be due to inefficient NADH oxidation and consequent lack of restoration of redox ratio." (PMID 37101412, 2023). "In the present studies, we also showed translational relevance of the effects of hyperammonemia in hiPSC‐derived myotubes that had protein hyperacetylation and lower Sirt3 expression with decreased mitochondrial oxidative function and impaired complex I response to substrates." (PMID 37101412, 2023). "Thus, using genetic and pharmacological approaches, we show that direct oxidation of NADH to restore NAD+ and redox ratio reversed lower Sirt3 expression and functional perturbations including protein hyperacetylation and mitochondrial oxidative dysfunction during hyperammonemia." (PMID 37101412, 2023). "Overexpression of Sirt3 reversed acetylation and senescence markers but not mitochondrial dysfunction while NR did not reverse the molecular or functional perturbations induced by hyperammonemia." (PMID 37101412, 2023).
Hypercholesterolemia (1 paper, 2024). An increased concentration of cholesterol in the blood. "Further, epigenetic regulation of intimal injury-SIRT3-FOXO3a-oxidative stress axis in the presence of intimal injury and hypercholesterolemia warrants further research." (PMID 38333571, 2024).
hyperthyroidism (1 paper, 2021). Overactivity of the thyroid gland resulting in overproduction of thyroid hormone and increased metabolic rate. "The RBP4/PiC/SIRT3 pathway is thus involved in the opening of the renal mPTP in offspring rats with hyperthyroidism." (PMID 33503180, 2021).
Interstitial cardiac fibrosis (1 paper, 2015). A type of myocardial fibrosis characterized by excessive diffuse collagen accumulation concentrated in interstitial spaces. "In a model of cardiac fibrosis, Sirt3−/− mice develop severe interstitial cardiac fibrosis and hypertrophy following application of a hypertrophic stimulus, whereas mice engineered to overexpress SIRT3 maintain normal cardiac structure and function." (PMID 26370974, 2015).
interstitial lung disease (1 paper, 2022). A diverse group of lung diseases that affect the lung parenchyma. "In SSc, the reduction in circulating SIRT1 and SIRT3 associated with a greater extent of cutaneous fibrosis, presence of interstitial lung disease, and worse pulmonary function." (PMID 35268452, 2022).
intestinal tumor (1 paper, 2023). "To focus on epithelial ablation of Sirt3 on intestinal tumor development, we generated AVS mice and observed a tumorigenic phenotype which further confirmed that Sirt3 restricts tumorigenesis at the initiation stage." (PMID 36739437, 2023).
intrauterine growth restriction (1 paper, 2025). "In placentas from fetuses with intrauterine growth restriction, the levels of the active form of SIRT3 protein are significantly reduced." (PMID 40881171, 2025).
iron overload (1 paper, 2021). "The activities of SOD2 and SIRT3 in BMMNCs from patients with iron overload were also significantly lower." (PMID 33435886, 2021). "Mitochondrial reactive oxygen species (mROS) levels, autophagy levels and the SIRT3/SOD2 pathway were examined in the models and in the bone marrow of patients with iron overload." (PMID 33435886, 2021).
ischemia reperfusion injury (1 paper, 2024). Adverse functional, metabolic, or structural changes in ischemic tissues resulting from the restoration of blood flow to the tissue (reperfusion), including swelling; hemorrhage; necrosis; and damage from free radicals. "In addition, studies indicated that SIRT3 can reduce ischemia-reperfusion injury and protect mitochondrial function by activating the anti-oxidant enzymes, suggesting that SIRT3 can be used to treat AKI ischemia-reperfusion injury." (PMID 38800015, 2024).
ischemic disease (1 paper, 2016). Lack of blood supply to an area of the body, resulting in impairment of tissue oxygenation. "Sirtuin 3 (SIRT3) mediates histone protein post-translational modification related to aging and ischemic disease." (PMID 26868537, 2016).
Kennedy disease (1 paper, 2024). Kennedy's disease, also known as bulbospinal muscular atrophy (BSMA), is a rare X-linked recessive motor neuron disease characterized by proximal and bulbar muscle wasting. "SIRT3 reduces protein degradation in the AR100Q mouse model, used to study neurodegenerative diseases like SBMA or Kennedy's disease, where mutations in the androgen receptor (AR) gene cause toxic effects on skeletal muscle, leading to muscle weakness and neurodegeneration." (PMID 38904020, 2024).
left ventricular hypertrophy (1 paper, 2020). Enlargement of the LEFT VENTRICLE of the heart. "Sirtuin-3 knockout mice displayed augmented left ventricular hypertrophy in response to TAC." (PMID 31980934, 2020).
Lewy body disease (1 paper, 2020). "Lastly, we assessed the level of SIRT3 in human post mortem brain with a confirmed neuropathological diagnosis of Lewy body disease (LBD)." (PMID 31931835, 2020).